GIP (gastric inhibitory polypeptide)
Diseases named in the same sentence as GIP in open-access papers (continued):
Sharing a sentence is not in itself a finding about the gene and the disease.
myocardial infarction (12 papers, 2017 to 2025). Gross necrosis of the myocardium, as a result of interruption of the blood supply to the area, as in coronary thrombosis. "Recently we found circulating GIP levels in patients with acute myocardial infarction to be associated with cardiovascular prognosis." (PMID 35123462, 2022). "Recently we found circulating GIP levels in patients with acute myocardial infarction to be associated with favorable cardiovascular prognosis." (PMID 35123462, 2022). "Beyond its metabolic function GIP has been found to exhibit direct cardio- and atheroprotective effects in mice and to be associated with cardiovascular prognosis in patients with myocardial infarction." (PMID 35123462, 2022). "Another strength of this study is the demonstration of an effect of a functional genetic variant in GIPR on CAD/myocardial infarction using the MR approach, suggesting an involvement of the GIP signalling pathway in the pathogenesis of CAD." (PMID 31974732, 2020). "Further, a two-sample Mendelian randomisation (2SMR) analysis between the GIP pathway and outcomes (coronary artery disease [CAD] and myocardial infarction) was carried out using a GIP-associated genetic variant, rs1800437, as instrumental variable." (PMID 31974732, 2020). "Additional support for an unfavorable vascular role for GIP comes from a large-scale genome-wide association meta-analysis reporting the correlation of a variant in the GIP gene with myocardial infarction." (PMID 31412576, 2019). "The underlying mechanism leading to the reduction of GIP after myocardial infarction or cardiac surgery remains currently unknown." (PMID 35123462, 2022). "For instance, genetic knockout of Gipr decreased LV remodeling and improved survival of mice after experimental myocardial infarction, whereas conversely human GIP has been reported to attenuate angiotensin II-induced cardiac hypertrophy and fibrosis." (PMID 39582036, 2024). "Circulating GIP levels are downregulated in patients with myocardial infarction and following cardiac surgery." (PMID 35123462, 2022). "The aim of this study was to characterize endogenous GIP levels in patients with acute myocardial infarction." (PMID 35123462, 2022). "This study demonstrates that circulating GIP levels are reduced in patients after acute myocardial infarction or cardiac surgery." (PMID 35123462, 2022). "In contrast to the findings, deleterious effects of GIP on cardiac remodeling were also reported in mouse models of myocardial infarction." (PMID 32098413, 2020). "Higher fasting GIP levels mediated via this variant have been linked to an increased risk of coronary artery disease (CAD) and myocardial infarction, though subsequent analyses suggested that fasting GIP and CAD associations are likely to be driven through distinct genetic signals at this locus." (PMID 37250804, 2023). "However, the associations between increased GIP levels and higher risk of CAD/myocardial infarction were confirmed using the large CARDIoGRAMplusC4D data in 2SMR analysis." (PMID 31974732, 2020). "To improve the reliability of our GIP to CAD/myocardial infarction MR analysis, we considered the possible confounding phenotypes and tested for their association with our instrumental variable rs1800437, which is associated with insulin secretion, BMI and other related phenotypes." (PMID 31974732, 2020). "Administration of GIP at the pharmacological dose may prevent the angiotensin II-induced cardiac hypertrophy, while inhibition of physiological levels of GIP could suppress the cardiac remodeling after myocardial infarction." (PMID 32098413, 2020). "We performed a 2SMR analysis by Wald ratio method between GIP levels as exposure and CAD (n = 184,305; 60,801 cases, 123,504 controls) and myocardial infarction (n = 171,875; 43,676 cases, 128,199 controls) as outcome variables in CARDIoGRAMplusC4D." (PMID 31974732, 2020).
myocardial infarction (continued). "One-week pre-treatment with [D-Ala2] GIP injections (24 nmol/kg body weight, twice daily), did not affect the mortality, but increased the left ventricle scar formation at two weeks after the induction of myocardial infarction in wild-type mice." (PMID 32098413, 2020). "Circulating GIP levels were significantly lower in patients with STEMI (ST-elevation myocardial infarction; n=100) compared to clinically stable patients without myocardial infarction (n=631) (216.82 pg/mL [Q1–Q3: 52.37–443.07] vs. 271.54 pg/mL [Q1–Q3: 70.12–542.41], p = 0.0266)." (PMID 35123462, 2022).
prediabetes (12 papers, 2015 to 2026). "The 2021 CETUS randomised placebo-controlled trial in individuals with new-onset prediabetes after acute pancreatitis showed that mild exogenous ketosis results in a 14.5% reduction in plasma glucose levels and a significant increase in GIP level." (PMID 33805259, 2021). "In this particular study, GLP-1 secretion was lower and GIP remained unchanged after 8 weeks of a whole-grain diet compared with a refined-grain diet in people with prediabetes." (PMID 30813546, 2019). "In the SURMOUNT-1 study, in fact, over 95% of participants with prediabetes were able to achieve normalization of blood glucose after 72 weeks of treatment with tirzepatide, the first GIP/GLP-1 receptor co-agonist representing this new class of drugs, compared to 62% of the control group." (PMID 38942960, 2024). "Therefore, it is suggested that the reduction in GLP-1 levels and/or a greater GIP resistance may contribute to impairment in insulin secretion in patients with prediabetes." (PMID 26146634, 2015). "It has been shown that patients with prediabetes exhibit decreased GLP-1 and unaltered GIP levels, as compared to those with normal glucose tolerance." (PMID 26146634, 2015). "However, the HP diet exhibited a higher prediabetes remission rate, possibly due to increased GLP-1 and GIP levels, enhancing insulin secretion and glucose handling." (PMID 38255264, 2024). "GIP action in prediabetes has not been established to date, so it is currently not clear if impaired GIP action is involved in T2D pathogenesis or manifests post-diagnosis." (PMID 34413662, 2021). "For Trial 3, only young male subjects without prediabetes were enrolled, and the effect of Jerusalem artichoke on the kinetics of GIP after a fat-rich meal in diabetic condition remains unclear." (PMID 35440936, 2022).
liver disease (11 papers, 2020 to 2026). "The GIP levels are elevated for a longer time in NASH patients after consuming saturated fat, and this enhanced GIP response is linked to the severity of liver disease." (PMID 37374119, 2023). "NASH patients exhibit a prolonged elevation of GIP after saturated fat ingestion and this increased GIP response to saturated fat intake is associated with the severity of liver disease." (PMID 33665203, 2021). "Hence, GLP-1 therapeutics that target glucagon (and GIP) may have advantages over selective GLP-1RA for liver diseases." (PMID 38161982, 2023).
Parkinson disease (11 papers, 2019 to 2026). A progressive degenerative disorder of the central nervous system characterized by loss of dopamine producing neurons in the substantia nigra and the presence of Lewy bodies in the substantia nigra and locus coeruleus. "Potential roles of GLP-1 signaling activators in neurodegenerative diseases have shown the neuroprotective effects of GLP-1 and GIP agonists in Alzheimer’s and Parkinson’s patients and murine models." (PMID 38791099, 2024). "This study proves that DA5‐CH can increase the expression of GDNF and BDNF in midbrain tissue, and provide a new direction for the study of the therapeutic mechanism of new GLP‐1/GIP dual agonists for Parkinson's disease." (PMID 34125470, 2021). "Both GLP-1 and GIP mimetics have shown neuroprotective properties in animal models of Parkinson’s and Alzheimer’s disease." (PMID 31998717, 2019). "GIP is found in the cerebrospinal fluid of mice and humans, which along with the demonstration that GIP analogues have neuroprotective effects in animal models of Alzheimer's and Parkinson's disease suggests that GIP is able to cross the blood–brain-barrier (BBB)." (PMID 40024571, 2025). "On the one hand, the effect of GIP signals on weight loss is transmitted through the central nervous system; on the other hand, GIP may have a neuroprotective effect on animal models of neurodegenerative diseases such as Alzheimer's disease and Parkinson's disease by promoting neurogenesis." (PMID 37096236, 2023). "Preclinical studies involving GIP and GLP-1R agonists have shown promising results in preclinical models of Parkinson’s disease, indicating their potential as a therapeutic target for both symptomatic relief and disease modification." (PMID 40003982, 2025). ".An experiment applied a second-generation novel GLP-1/GIP dual receptor agonist, DA3-CH, to an MPTP-induced Parkinson’s mouse model and compared its neuroprotective effects with the GLP-1 single receptor agonist, liraglutide." (PMID 39719978, 2024). "While considerably less is known about the CNS effects of GIP compared to GLP-1 and glucagon, dual GIP/GLP-1 RA treatment has shown positive effects on animal models of Alzheimer’s disease and Parkinson’s disease (Hölscher, 2018)." (PMID 31133864, 2019).
Alzheimer disease (10 papers, 2013 to 2025). A progressive, neurodegenerative disease characterized by loss of function and death of nerve cells in several areas of the brain leading to loss of cognitive function such as memory and language. "By contrast, other studies reported anti-inflammatory effects of GIP, including a reduction in neuroinflammation surrounding amyloid plaques in a mouse model of Alzheimer’s disease after chronic treatment with [D-Ala2]GIP or a dual GLP1R/GIPR agonist." (PMID 40166681, 2025). "Agonist analogs of GIP reduce central oxidative stress, and are neuroprotective in Alzheimer’s disease, and stroke models." (PMID 28413428, 2017). "Furthermore, recent in vivo studies have demonstrated multiple beneficial effects of GIP on diabetes-related diseases, such as Alzheimer’s disease and osteoporosis." (PMID 32098413, 2020).
liver fibrosis (9 papers, 2012 to 2025). "Phase 2 trials with liver-directed mechanisms (Efruxifermin, Pegozafermin) that target FGF-21 or weight-loss combinations of GLP-1/GIP/Glucagon (Tirzepatide, Survodutide) have shown improvement in liver fibrosis and are currently in phase 3 investigations." (PMID 39589962, 2024). "As expected, dual GIP/GLP-1RA, GCGR/GLP-1RA and GLP-1RA treatments significantly reversed liver fibrosis and reduced intrahepatic lipid percentage." (PMID 41246119, 2025). "All studies showed the superiority of dual GIP/GLP-1RA, GCGR/GLP-1RA or GLP-1RA to reverse the liver fibrosis degree by at least one stage in individuals with MASLD and T2D." (PMID 41246119, 2025). "Hence the increased levels of GIP, adipsin and insulin as well as of leptin, that augments insulin signal transduction, are mainly correlated not only between them but also with the decreased levels of ghrelin that has been indicated as marker of the liver fibrosis progression." (PMID 22745767, 2012). "Dual GIP/GLP-1RA, GCGR/GLP-1RA and GLP-1RA were significantly superior in reversing the liver fibrosis degree (OR 3.72; 95% CI: 2.72, 5.09; p<0.001) and decreasing the LFC (MD -18.90; 95% CI: -18.43, -19.37; p<0.001) compared with other active therapies or placebo." (PMID 41246119, 2025). "For this, we explored the possibility that the beneficial actions of GLP-1/GIP dual agonism in the liver of animals and patients with MASH could be exerted through actions within two of the most relevant cell populations involved in the progression of liver fibrosis: hepatocytes and HSCs." (PMID 39607493, 2024).
steatosis (9 papers, 2012 to 2025). Increased lipid within the cytoplasm of cells. "Liver sections from WT mice at 18 weeks exhibited marked steatosis following the HF diet, but the GIP overexpressing mice showed a remarkable attenuation of hepatic lipid accumulation." (PMID 22802954, 2012). "On the contrary, GIP knockout mice fed an HFD had decreased steatosis and inflammation, evaluated by lower levels of IL-6, indicating that GIP may promote lipid deposition and inhibition and that signaling could protect from that." (PMID 38612640, 2024). "In our study, increased ALT, GGT, and FLI associated with normal CK-18 (M30) suggest elevated risk for simple steatosis, but not steatohepatitis in high GIP subjects, without symptoms of advanced hepatocytes apoptosis." (PMID 32069846, 2020). "Moreover, it should be acknowledged that novel pharmacotherapeutic interventions which promote weight loss including the glucagon-like peptide 1 (GLP-1) receptor and gastric inhibitory polypeptide (GIP) agonists hold promise in reducing steatosis of possible donors." (PMID 38725471, 2024). "In line with earlier studies demonstrating that subcutaneous administration of long-acting GIP analogues resulted in improved β-cell function and glycemic control, GIP Tg mice showed improved insulin sensitivity, glucose tolerance and β-cell function, as well as reduced steatosis." (PMID 22802954, 2012). "Tirzepatide, a novel GIP/GLP1-RA, seems promising; however, its efficacy in terms of steatosis management remains to be established." (PMID 37770761, 2023). "It is therefore likely that reduced steatosis and adipocyte macrophage infiltration plus altered WAT signaling all contributed to the improved metabolic profiles of the Het GIP Tg mice on the HF diet, including the improved insulin sensitivity." (PMID 22802954, 2012). "Of note, pharmacological treatment with GLP-1/GIP in a mice model of MASH seemed to further reduce steatosis, inflammation, and potentially, fibrosis and liver dysfunction enzymes, as well as ameliorating lipid and glycemic profile, compared with GLP-1 and GIP mono-agonists." (PMID 38612640, 2024). "Besides steatosis, GLP-1/GIP RAs ameliorated MASH by reinforcing hepatic insulin sensitivity, enhancing triglyceride lipolysis, and restricting the supply of free fatty acids in the liver." (PMID 38612640, 2024). "Empirical evidence suggests that sitagliptin might improve steatosis by suppressing lipogenic and gluconeogenic pathways through the inhibitation of DPP-4 and increasing levels of biological activity of GLP-1 and GIP." (PMID 35966875, 2022).
Abdominal obesity (8 papers, 2016 to 2025). Excessive fat around the stomach and abdomen. "GLP-1 and GIP agonist use has been shown to reduce MetS severity, abdominal obesity, and inflammation." (PMID 40146920, 2025). "Against the background of abdominal obesity, the probability of having chronic bronchitis increased with an increase in the level of lipocalin-2 and GIP and TNFa." (PMID 36291711, 2022).
chronic kidney disease (8 papers, 2023 to 2025). Impairment of the renal function secondary to chronic kidney damage persisting for three or more months. "The increase in GIP levels in uremic patients or those with chronic kidney disease, along with the decreased GIP clearance in nephrectomized rats, suggests that the kidneys are the main system for GIP clearance." (PMID 40649920, 2025). "The circulating level of endogenous GIP depends on renal metabolism and is elevated in people with chronic kidney disease." (PMID 37623488, 2023).
coronary artery disease (8 papers, 2018 to 2026). "Previous work selected a variant to proxy GIP signalling based on its relation to fasting GIP levels, and in contrast to our current findings produced MR results to support a detrimental effect of GIP signalling on coronary artery disease risk." (PMID 34505161, 2021). "Incretin hormones such as glucagon-like peptide-1 (GLP-1) and glucose-dependent insulinotropic polypeptide (GIP), along with trimethylamine N-oxide (TMAO), have been implicated in the pathogenesis of coronary artery disease (CAD)." (PMID 41751159, 2026).
obstructive sleep apnea (8 papers, 2024 to 2026). "Although we mention only a few of the most prominent clinical trials, liraglutide and tirzepatide show consistent efficacy of GLP-1 and GIP/GLP-1 receptor agonists in obstructive sleep apnea settings." (PMID 39768911, 2024). "Therefore, the GLP-1 and GIP/GLP-1 receptor agonists in this clinical setting have value in their weight reduction potential and glucose metabolism normalization as well as cardiovascular risk reduction and could even progress to first-line therapy for obstructive sleep apnea." (PMID 39768911, 2024).
gestational diabetes (7 papers, 2020 to 2025). Carbohydrate intolerance first diagnosed during pregnancy. "Data related to postprandial GIP levels under conditions of gestational diabetes (GD) are conflicting, with GIP responses to oral glucose or fat being mildly reduced or increased." (PMID 40024571, 2025). "Studies of incretins in pregnancy have largely been focussed on circulating GLP-1 and GIP concentrations in gestational diabetes, hyperglycaemia that first develops or is first recognised during pregnancy." (PMID 37439859, 2023). "However, the number of participants in which GIP concentrations were measured were at least comparable to those in a number of other studies of incretin concentrations in gestational diabetes." (PMID 37439859, 2023). "Glucagon-like peptide 1 (GLP-1) and glucose-dependent insulinotropic peptide (GIP) may be involved in pathogenesis of gestational diabetes mellitus (GDM)." (PMID 36717953, 2023). "Summarizing these data, levels of GIP change only minimally during pregnancy and gestational diabetes, and GIP does not seem to play a major role in the metabolic adaptation to pregnancy or lactation." (PMID 40024571, 2025). "The consistent results largely relate to the fasting concentrations of GLP-1 and GIP not being altered in women with gestational diabetes in the present study." (PMID 37439859, 2023).
non-alcoholic steatohepatitis (7 papers, 2020 to 2026). "Beyond the heart and kidneys, SGLT2is, and particularly GLP-1RAs and GIP/GLP-1RAs, have shown promise in MASLD (formerly known as non-alcoholic fatty liver disease—NAFLD) and MASH (formerly known as non-alcoholic steatohepatitis—NASH)." (PMID 39857719, 2025).